DRD4 (dopamine receptor D4)
Description:
Dopamine receptor responsible for neuronal signaling in the mesolimbic system of the brain, an area of the brain that regulates emotion and complex behavior. Activated by dopamine, but also by epinephrine and norepinephrine, and by numerous synthetic agonists and drugs. Agonist binding triggers signaling via G proteins that inhibit adenylyl cyclase. Modulates the circadian rhythm of contrast sensitivity by regulating the rhythmic expression of NPAS2 in the retinal ganglion cells (By similarity).
Synonyms: D4DR
Tractability: Small molecule: an approved drug acts on it; a structure with a bound ligand is known; a high-quality ligand is known; it belongs to a druggable protein family. Antibody: UniProt places it where antibodies can reach, with high confidence; its Gene Ontology location is reachable by antibodies, with high confidence; UniProt predicts a signal peptide or a membrane-spanning region. PROTAC: UniProt records ubiquitination sites on it; a small molecule that binds it is known. Other modalities: an approved drug acts on it.
Target class: Small molecule receptor (family A GPCR); Dopamine receptor; Family A G protein-coupled receptor; Monoamine receptor; Membrane receptor
Chemical probes: A-369724 (high quality), L-745870 (high quality), ML398, UCSF924 (high quality)
Gene: Protein-coding gene on chromosome 11 (637,269 to 640,706, forward strand). Ensembl gene ENSG00000069696.
Subcellular location: Cell membrane
Subcellular location (Human Protein Atlas): Plasma membrane; Centrosome
Pathways (Reactome):
Signal Transduction: Dopamine receptors; G alpha (i) signalling events
Gene Ontology:
Molecular function: adrenergic receptor activity; dopamine binding; dopamine neurotransmitter receptor activity; dopamine neurotransmitter receptor activity, coupled via Gi/Go; epinephrine binding; identical protein binding; norepinephrine binding; protein binding; SH3 domain binding; G protein-coupled serotonin receptor activity; neurotransmitter receptor activity; potassium channel regulator activity; G protein-coupled receptor activity
Biological process: adenylate cyclase-inhibiting dopamine receptor signaling pathway; adenylate cyclase-inhibiting G protein-coupled receptor signaling pathway; arachidonate secretion; intracellular calcium ion homeostasis; negative regulation of protein secretion; phospholipase C-activating dopamine receptor signaling pathway; positive regulation of MAPK cascade; response to histamine; adenylate cyclase-modulating G protein-coupled receptor signaling pathway; adult locomotory behavior; behavioral fear response; behavioral response to cocaine; behavioral response to ethanol; chemical synaptic transmission; fear response; G protein-coupled receptor signaling pathway, coupled to cyclic nucleotide second messenger; inhibitory postsynaptic potential; locomotory exploration behavior; positive regulation of dopamine uptake involved in synaptic transmission; regulation of circadian rhythm; regulation of dopamine metabolic process; response to amphetamine; social behavior; adrenergic receptor signaling pathway; adult behavior; and 5 more
Cellular component: membrane; plasma membrane; dendrite; glutamatergic synapse; postsynapse
Genetic constraint (gnomAD): Loss-of-function variants: 28 observed, 16.67 expected, observed/expected ratio (o/e) 1.68, 90% interval 1.22 to 1.95. The synonymous counts are far from expectation, so gnomAD's model fits this gene poorly and the ratio says little. Missense variants: 911 observed, 517.21 expected, observed/expected ratio (o/e) 1.76, 90% interval 1.67 to 1.86. Synonymous variants: 455 observed, 257.14 expected, observed/expected ratio (o/e) 1.77, 90% interval 1.64 to 1.91.
Homologues: Orthologues: chimpanzee DRD4 (96% identical), macaque DRD4 (94% identical), mouse Drd4 (73% identical), rat Drd4 (72% identical), pig DRD4 (72% identical), dog DRD4 (70% identical), tropical clawed frog drd4 (50% identical), zebrafish drd4a (49% identical), zebrafish drd4b (49% identical). Paralogues in human: DRD3 (36% identical), HTR1A (29% identical), DRD5 (26% identical), DRD1 (26% identical), CHRM1 (25% identical), CHRM4 (25% identical), HRH2 (25% identical), HTR1D (24% identical), CHRM3 (24% identical), HTR4 (24% identical), HRH1 (23% identical), HRH3 (23% identical), and 13 more.
Diseases named in the same sentence as DRD4 in open-access papers:
DRD4 is named in the same sentence as 125 diseases in open-access papers, as found by Europe PMC text mining. Sharing a sentence is not in itself a finding about the gene and the disease. The quoted sentences say what the papers report.
schizophrenia (46 papers, 2008 to 2025). A major psychotic disorder characterized by abnormalities in the perception or expression of reality. "Patients carrying the DRD4 D4.2 and D4.3 alleles were more frequently diagnosed with catatonic schizophrenia compared to other schizophrenic cases and controls." (PMID 41368066, 2025). "DRD4 rs1800955 was associated with mental illnesses in the general group of psychiatric disorders and in the subgroups of schizophrenia and mood disorders separately." (PMID 38397229, 2024). "Different studies previously reported genetic variants in the upstream DRD4 region with various neurobehavioral disorders such as novelty seeking, schizophrenia, attention-deficit/hyperactivity disorder, and substance abuse." (PMID 33544778, 2021). "Network 1 included, as well as Npy and Bdnf, several transcripts involved in neurotransmission and implicated in schizophrenia, such as dopamine D1 and D4 receptors (Drd1 and Drd4)." (PMID 30348978, 2018). "It was revealed that methylation levels at the promoter of the DRD4 gene are associated with schizophrenia, Alzheimer’s disease, drug addiction and alcohol dependence." (PMID 29551965, 2018). "DRD4 is one of the most widely implicated genes in the pathology of both schizophrenia and bipolar disorder as well as many other neuropsychiatric disorders." (PMID 25010591, 2014). "The present study examined DRD4 C-521T, a SNP in the promoter region of the gene encoding the DA D4 receptor protein, based on evidence of its association with schizophrenia and the observation that T-homozygotes have a larger ERN amplitude than C-homozygotes." (PMID 25010186, 2014). "The polymorphism of DRD4 in humans is known to link with neurological and psychiatric conditions such as schizophrenia, Parkinson's disease, addictive behaviors, eating disorder, and longevity." (PMID 25078403, 2014). "The DRD4 -521C allele has been associated with schizophrenia and healthy individuals homozygous for the C allele showed a decreased ERN and decreased post-error slowing compared to T homozygotes." (PMID 23882201, 2013). "The VNTR polymorphism in DRD4 has been reported previously to be involved in the pathogenesis of schizophrenia." (PMID 20040103, 2009). "Other than socio-psycho-physiological factors, the dopamine D4 receptor (DRD4) gene was found to be associated with schizophrenia, which serve as an important genetic component confer to disease susceptibility." (PMID 23675088, 2008). "Second, the interaction between DRD4 and the IL-10 polymorphism in schizophrenia was further investigated." (PMID 23675088, 2008). "Moreover, mutations in the DRD4 gene have been associated with various behavioural phenotypes, including acute psychosis and schizophrenia." (PMID 29221470, 2017). "In addition, a meta-analysis that was based on more than 1000 association studies of schizophrenia identified 16 genes that were mostly biogenic amine-related, including dopamine receptor D4." (PMID 29221470, 2017).
schizophrenia (continued). "However, the long form alleles (≥ 5 repeats) of the DRD4 uVNTR polymorphism were more frequent in patients with schizophrenia than in controls (p = 0.001)." (PMID 20040103, 2009). "A genetic study of schizophrenia found an association with the longer allele on the DRD4 gene, whereas the rs1800955 C allele-which may lead to higher expression of DRD4 mRNA-was associated with schizophrenia." (PMID 20046399, 2009). "Previously, we have reported that the long form alleles of the uVNTR polymorphism in DRD4 might a risk factor for vulnerability to schizophrenia." (PMID 20040103, 2009). "In addition, association have been found between DRD2 and DRD4 polymorphisms and novelty seeking, substance abuse and impulsivity behavior, as well as schizophrenia and mood disorders." (PMID 28054193, 2018). "Associations of rs6265 in BDNF, rs1800955 in DRD4, and rs6313 in HTR2A with schizophrenia in patients from the schizophrenia group separately compared to the control group were also found." (PMID 38397229, 2024). "This study aimed to investigate the association between four polymorphisms in DRD2, DRD4 and COMT genes and their gene-gene interactions with antipsychotic treatment response in patients with schizophrenia." (PMID 37880658, 2023). "Polymorphic variants in SLC6A4, MAOA, DRD4, and DRD2 have shown statistical associations with major depressive disorder, anti-social behaviour, schizophrenia, and bipolar disorder." (PMID 33809805, 2021). "In this context it is important to note that the DRD4 specifically was found to be expressed in excess in the striatum in postmortem brains of schizophrenia patients." (PMID 26157401, 2015). "For example, studies of schizophrenia have revealed synergistic SNP-SNP interactions in dopamine receptor D4 (DRD4) and in neuregulin 1 (NRG1)/v-erb-a erythroblastic leukemia viral oncogene homolog 4 (avian) (ERBB4)/AKT1 genes." (PMID 24955105, 2014). "Much of the emphasis has been upon the exon 3 VNTR, yet SNPs in the DRD4 promoter have also shown significant associations with ADHD, schizophrenia and fibromyalgia." (PMID 22691691, 2012). "This interaction may stem from shared genetic pathways involving dopamine regulation and Dopamine Receptor D4 (DRD4) in treatment-resistant schizophrenia (TRS), where alcohol potentiates clozapine’s adverse effects." (PMID 41479675, 2025). "More recent work has confirmed such epistatic gene-gene interactions, for instance, by showing that COMT and DRD3 together modulate behavior in children with ADHD and that DRD4 in combination with COMT modulate the clinical responses to clozapine in schizophrenia patients." (PMID 33328916, 2020). "The genes for platelet-derived growth factor beta (PDGFB) and PDGFB receptor (PDGFBR) may be important in the pathology of schizophrenia through interacting with the DRD2/DRD4 and NMDA receptors." (PMID 28117656, 2016). "Also, DRD4, a top upstream regulator identified in the shared DMR gene set, has been previously implicated in schizophrenia, and is thought to be the target of many antipsychotics." (PMID 25943100, 2015). "The DA D4 receptor gene (DRD4) is also a candidate gene for schizophrenia and the −521 single nucleotide polymorphism (SNP) refers to a C-to-T substitution in the DRD4 promoter region (rs1800955) with the T allele resulting in 40% less transcriptional efficiency." (PMID 23882201, 2013).
schizophrenia (continued). "Therefore, how the alteration of DRD4 expression relates to the etiology of schizophrenia remains controversial." (PMID 20046399, 2009). "The research also established a link between rs6265 in BDNF, rs1800955 in DRD4, and rs6313 in HTR2A and schizophrenia in patients with schizophrenia spectrum disorder compared to the control group." (PMID 38397229, 2024). "Parallel and multistep analysis in this research showed that SLC1A1, DRD2, DRD4, BDNF, ESR1, CDH2, GRIN2B, TNFa, GABBR1, and OLIG2 are common genes between schizophrenia and OCD which ESR1, DRD2, GABBR1, TNFa, and CDH2 are the most important individuals." (PMID 31086558, 2018). "Candidate gene studies have often been focused on the role of dopamine receptors and related genes (namely DRD1, DRD2, DRD3, DRD4, and DRD5) as modulators of antipsychotic drug responsiveness and schizophrenia symptoms." (PMID 30687136, 2018). "In other studies, DRD4 levels in postmortem brain tissue from MDD and schizophrenia patients were found to be elevated." (PMID 24826212, 2014). "The dopamine receptor gene DRD4 is being intensively studied with regard to its possible involvement in several mental disorders, such as attention deficit disorder (ADHD), gambling addiction, alcoholism, drug addiction, and schizophrenia." (PMID 33868590, 2021). "In this work, we analyzed 28 studies conducted from 1989 to 2021, studying 37 genetic variations, including SNVs/polymorphisms of four candidate dopamine receptor genes (DRD1, DRD2, DRD3, DRD4) involved in the development of AIP and AITD in patients with schizophrenia." (PMID 34440083, 2021). "Several genes were validated in APA sperm that were associated with autism spectrum disorder (CACNA1H, CNTNAP2, GRIN1, SHANK2, SHANK3, ZNF804A), schizophrenia (TCF3, ZNF804A), and bipolar disorder (COMT, DRD4, GRIN1, MBP, PRKCZ, SHANK2, TRPM2, ZNF804A), and in APA blastocysts (CACNA1H)." (PMID 32610362, 2020). "Moreover, the DRD4 C-521T effect on ERN amplitude was significant in the schizophrenia group alone, making this the first report of this effect in schizophrenia." (PMID 25010186, 2014).
depression (29 papers, 2004 to 2025). "Using the linear discriminant analysis, DAT and DRD4 showed significant associations with depression in DLB." (PMID 40113786, 2025). "According to previously published reports, the DRD4 VNTR variants with a higher number of repeats tended to predispose to depression and other mental disorders." (PMID 33868590, 2021). "Of note, other studies reported a negligible association between the DRD4 gene polymorphism and depression symptoms, which is in agreement with our findings." (PMID 33784353, 2021). "A significant association between the 48 bp repeat polymorphism of DRD4 and depression was reported." (PMID 26733829, 2015). "In a combined sample, a significant interaction was seen between depression and DRD4, in which depressed smokers homozygous for the short alleles of DRD4 were more likely to smoke to reduce negative feelings and to smoke in response to stimulation." (PMID 19570274, 2004). "Hence, there is a high frequency of genotypes with the long allele of the DRD4 exon 3 in males with anxiety, depression, and vital exhaustion." (PMID 34828440, 2021). "Variants of DRD4 could also modulate the response to treatment in patients with depression." (PMID 33784353, 2021). "Expression of FKBP5 is reported to be GRE regulated, and Drd4 is a reported biomarker of depression." (PMID 37819629, 2024). "Subsequent three approaches were aimed to analyse the impact of the DRD4 agonist on depression-like and anhedonic behaviour and included FST, NSF, and SPT." (PMID 36854793, 2023). "Several clinical genetic linkage studies demonstrate possible correlations between DRD4 expression and substance use disorders, as well as depression." (PMID 34828440, 2021). "The association of DRD4 and SLC6A4 genetic polymorphisms with anxiety and depression in HD patients was also assessed after adjusting for demographic and clinical covariates." (PMID 33784353, 2021). "The DRD4 gene and 5-HTTLPR gene polymorphisms play a key role in the etiology of attention deficit and hyperactivity disorder and depressive disorder respectively." (PMID 29364853, 2018). "DRD4 genotype was unrelated to maternal age and depression, child sex, and maternal interactive sensitivity at 6-months postpartum in the overall sample (data not shown), and among European-ancestry children." (PMID 27494520, 2016). "Significant associations between DRD2, DRD4, and COMT polymorphisms and the risk of depression, as well as the severity of depressive symptoms, were reported." (PMID 26733829, 2015). "Thus, the battery of tests, which was designed to measure anxiety and depression-like behaviour, indicated sporadic anxiolytic and antidepressant effects of DRD4 agonism." (PMID 36854793, 2023). "Supporting this hypothesis, PBMCs from patients with untreated depression had significantly lower levels of Drd4 mRNA than healthy control subjects." (PMID 36757901, 2023). "Genotype and allele frequencies of DRD4 and SLC6A4 polymorphisms by depression and anxiety status." (PMID 33784353, 2021). "Thus, the objective of this study was to examine the association of DRD4 and SLC6A4 genetic polymorphisms with depression or anxiety in HD patients in Jordan." (PMID 33784353, 2021). "The effect of DRD4 and SLC6A4 polymorphisms on depression adjusting for other covariates." (PMID 33784353, 2021). "Further, specificity tests of genetic associations could be extended by accounting for other candidate genes implicated in depression risk (e.g., HOMER1, TPH, DRD4, COMT)." (PMID 24312122, 2013). "In this study, we estimated the contribution of SLC6A4 (5HTT), HTR1A, HTR2A, HTR1B, SLC6A3 (DAT1), DRD4, DRD2, COMT, and BDNF genes to the suicidal behavior and severity of symptoms of depression and anxiety in the East-Slavic population of Russia." (PMID 34199792, 2021).
depression (continued). "This study aims to estimate the contribution of 11 polymorphisms in the genes SLC6A4 (5HTT), HTR1A, HTR2A, HTR1B, SLC6A3 (DAT1), DRD4, DRD2, COMT, and BDNF to suicidal behavior and severity of symptoms of depression and anxiety in the Russian population." (PMID 34199792, 2021). "Therefore, we evaluated the effect of coadministration of DRD4 antagonist with CB2R agonist or antagonist in anxiety-like and depression-like behaviors." (PMID 40365131, 2025). "Altogether, the present study shows that the activation of DRD4 has little impact on anxiety-related and depression-like behaviour, nor on the reinforcing properties of alcohol in mice." (PMID 36854793, 2023). "No main effect of DRD4 on depression, stimulation smoking, negative-affect reduction smoking or nicotine dependence." (PMID 19570274, 2004).